PCNA (proliferating cell nuclear antigen)
Diseases named in the same sentence as PCNA in open-access papers (continued):
Sharing a sentence is not in itself a finding about the gene and the disease.
osteosarcoma (continued). "Osteosarcoma patients with low PCNA expression were found to have higher OS than those with high PCNA expression (RR = 1.54, 95% CI 1.02–2.31; P = .038)." (PMID 29019895, 2017). "The findings from this meta-analysis indicate that PCNA overexpression is an effective biomarker for poor prognosis in patients with osteosarcoma for OS." (PMID 29019895, 2017). "In our study, 6 studies provided valuable information to estimate the prognostic role of PCNA expression in patients with osteosarcoma at disease-free survival (DFS)." (PMID 29019895, 2017). "In summary, the findings from this meta-analysis suggested that PCNA expression is an effective biomarker for poor prognosis in patients with osteosarcoma for OS." (PMID 29019895, 2017). "Compared with low PCNA expression, high PCNA expression was correlated with a poor prognosis in OS of osteosarcoma (RR = 1.84, 95% CI 1.41–2.40; P = .000)." (PMID 29019895, 2017). "The purpose of this meta-analysis is to determine the prognostic role of PCNA in patients with osteosarcoma." (PMID 29019895, 2017). "More importantly, the percentages of anti-PCNA positively stained proliferative osteosarcoma cells in the ALA-SDT group of tumors were significantly lower than that of the ultrasound-treated tumors (p<0.05)." (PMID 26161801, 2015). "To understand the therapeutic mechanisms of ALA-SDT in vivo, we analyzed the proliferative osteosarcoma cells in the implanted tumors by anti-PCNA staining." (PMID 26161801, 2015). "To study the interaction of p66 with PCNA further we used various constructs expressing p66 in human U2OS osteosarcoma cells as fusions with Enhanced Green Fluorescent Protein (EGFP)." (PMID 16000169, 2005). "Additionally, silencing PTPN23 promotes osteosarcoma cell proliferation by modulating cell cycle proteins, such as PCNA, indicating its mechanistic role in tumorigenesis and its potential as a therapeutic target." (PMID 40570022, 2025). "Notably, in U2OS osteosarcoma cells, inhibiting the interaction between PCNA and DNA polymerase η (POLH) blocks DNA damage repair and suppresses U2OS cell proliferation." (PMID 40508066, 2025). "Overall, our findings suggest that high expression or co-expression of USP37 and PCNA could be a predictor of therapeutic outcome in osteosarcoma patients." (PMID 37118828, 2023). "Taken together, the immunohistochemistry study supports the findings from the in vitro and in silico experiments and suggests that USP37 and PCNA may play important roles in the progression of osteosarcoma." (PMID 37118828, 2023). "The interaction between USP37 and PCNA is involved in the regulation of replication stress, and disrupting it could potentially trigger synthetic lethality in osteosarcoma." (PMID 37118828, 2023). "In this study, we revealed that SRPK1 may regulate cell proliferation molecules such as PCNA and Ki67 to play a critical role in osteosarcoma cell proliferation and tumor progression." (PMID 36038837, 2022). "Meta-analysis of these 3 studies showed no statistical association between PCNA expression and OS of osteosarcoma (RR = 1.68, 95% CI 1.16–2.43; P = .006)." (PMID 29019895, 2017). "The meta-analysis suggested that PCNA overexpression in osteosarcoma patients is associated with low OS, but not significantly with DFS (RR = 1.82, 95% CI 1.53–2.18, P = .000; RR = 1.15, 95% CI 0.91–1.44, P = 0.234)." (PMID 29019895, 2017). "Therefore, we conducted a meta-analysis to further investigate this prognostic value, and discussed the possibility of PCNA as a prognostic medical marker in osteosarcoma." (PMID 29019895, 2017). "PCNA overexpression was found in approximately 57.31% of the patients with osteosarcoma." (PMID 29019895, 2017).
osteosarcoma (continued). "In addition, the ALA-SDT significantly reduced the percentages of PCNA+ rat osteosarcoma cells in the tumors." (PMID 26161801, 2015). "Interestingly, higher PCNA associated with cell proliferation was present in pre-chemotherapy biopsies in high-grade metastatic (META) vs. non-metastatic (NON-META) osteosarcoma." (PMID 40507884, 2025). "In continuation to our previous study, we have provided evidence here that USP37 interacts with PCNA, which is a critical protein in replication fork movement, by functioning as a sliding clamp loader, thereby regulating replication stress tolerance in osteosarcoma cells." (PMID 37118828, 2023). "Nevertheless, the roles of HDAC4 and PCNA in osteosarcoma (OS) remain unclear." (PMID 31552187, 2019). "Our results show an association between allergic airway inflammation and extensive lung metastasis of osteosarcoma in a comorbidity mouse model with elevated expression of TGF-β and PCNA." (PMID 40507884, 2025). "Our findings show that in osteosarcoma cells, USP37's interaction with PCNA plays a role in supporting the stability of the replication fork." (PMID 37118828, 2023). "Multiple studies have attempted to explore the relationship between PCNA expression and OS or DFS in osteosarcoma but the sample size of these studies was small, which weakened the reliability of their result." (PMID 29019895, 2017). "Clinically, higher PCNA levels were detected in metastatic vs. non-metastatic osteosarcoma, representing a poor prognosis for these patients." (PMID 40507884, 2025). "Furthermore, immunohistochemistry was performed on archived tissue blocks from osteosarcoma patients to establish a correlation between USP37 and PCNA expression." (PMID 37118828, 2023). "In osteosarcoma cells, HDAC4 promotes cell proliferation through the regulation of PCNA expression." (PMID 35242053, 2022). "Meta-analysis of these 6 studies showed no statistical association between PCNA expression and DFS of osteosarcoma (RR = 1.15, 95% CI 0.91–1.44, P = .234)." (PMID 29019895, 2017). "Numerous studies have attempted to determine the prognostic role of proliferating cell nuclear antigen (PCNA) expression in patients with osteosarcoma with no consistent conclusion." (PMID 29019895, 2017). "Meta-analysis of these 6 studies showed no statistical association between PCNA overexpression and DFS of osteosarcoma (RR = 1.15, 95% CI 0.91–1.44, P = .234)." (PMID 29019895, 2017). "In comparison with that in the Control group of tumors, ultrasound, but not 5-ALA, treatment significantly reduced the frequency of anti-PCNA positively stained proliferative osteosarcoma cells (p<0.05) and ALA-SDT further reduced the percentages of proliferative osteosarcoma cells (p<0.01)." (PMID 26161801, 2015). "Furthermore, expression profiles of several proteins interacting with PCNA in cell proliferation-related processes showed upregulation in metastatic (META) vs. non-metastatic (NON-META) osteosarcoma." (PMID 40507884, 2025). "Our analysis revealed that USP37 levels were significantly higher in osteosarcoma tissues as compared to non-transformed tissue and that the expression of USP37 had a positive correlation with PCNA expression." (PMID 37118828, 2023). "Furthermore, the high PCNA index observed in our cases, support the opinion that TFR expression could be related to the proliferative activity of neoplastic cells, which is related to the malignant behaviour in canine osteosarcomas (Dolkaet, Sapierzyński, & Król, 2013)." (PMID 32239803, 2020).
diabetes (22 papers, 2011 to 2024). "In addition, statins decreased diabetes-associated renal dysfunction (albuminuria) and prevented renal damage and cell proliferation, as evidenced d by PCNA protein expression and immunolocalization." (PMID 27649495, 2016). "Another protein that is compromised in diabetes patients is the proliferating cell nuclear antigen (PCNA) protein, which is involved in DNA replication, repair, and cell cycle regulation." (PMID 39201678, 2024). "In the diabetes+IE group, it was observed that the number of PCNA positive cells increased compared to the diabetes group." (PMID 37098926, 2023). "There was a statistically significant difference in PCNA index values between control, diabetes and diabetes+IE groups." (PMID 37098926, 2023). "In the control group, many spermatocytes and spermatogonium in the seminiferous tubules showed PCNA positive reaction, whereas in the diabetes group it was less than the control group." (PMID 37098926, 2023). "For example, spontaneous diabetes in a zebrafish model recovered rapidly following chemical treatment, due to PCNA-Pdx1 positive cells differentiating into β-cells." (PMID 32375753, 2020). "Enhanced PCNA activity was evident in both hepatocytes and cholangiocytes during infection and/or diabetes, particularly in the OD hamsters." (PMID 29953446, 2018). "PCNA protein level was significantly lower (P < 0.05) in the diabetes group than in the control group." (PMID 30237484, 2018). "MLT treatment impeded apoptosis (p = 0.02) and augmented proliferation (p = 0.0008) and PCNA content in prostate following long-term diabetes due to restoration of testosterone levels and expression of melatonin receptor type 1B." (PMID 26295055, 2015). "Kidney PCNA mRNA and the number of positive cells found in glomeruli were significantly increased in diabetes mice compared with those in control mice." (PMID 24672545, 2014). "Considering the significant increase in PCNA+ β-cells in patients with diabetes, we then examined alterations in expression of proteins that regulate cell-cycle." (PMID 22140505, 2011). "In a study using a model of severe diabetes induced by alloxan, a direct relationship was established between hyperglycemia and low PCNA expression in rat myometrial cells, with hormonal dysfunction caused by hyperglycemia being responsible for intense cell proliferation." (PMID 37892483, 2023). "Here in this study, we found that diabetes likely affected the phenotype of macrophages in such a delicate manner, since diabetes seemed to alter the levels of markers for macrophage functionality, iNOS, TNFα and IFNγ, and the levels of PCNA, a cell proliferation marker." (PMID 36405726, 2022). "Previous studies have demonstrated that the increase in PCNA expression in testicular tissue is an indication of high proliferative activity and stimulation of spermatogenesis, and this expression is downregulated in diabetes." (PMID 27869771, 2016). "Moreover, El-behery and colleagues in 2019 showed a PCNA+ (Proliferating cell nuclear antigen) cell number reduction in diabetes-induced hyperglycemia condition, which led to the conclusion that there is a reduced DNA repair mechanism in diabetic rat testicular tissue." (PMID 38164482, 2024). "Histological changes due to complications of diabetes were demonstrated by TUNEL and PCNA methods in testicular tissues of diabetes-induced rats by STZ." (PMID 37098926, 2023). "The high-dose PCE treatment markedly reduced these diabetes-induced increases in α-SMA and PCNA expression." (PMID 25495844, 2014). "Most importantly, PCNA transcript and the number of PCNA-positive cells were significantly decreased in fxB mice as compared with the diabetic BKS.Cg db/db mice, implying suppression of DMH-induced diabetes-promoted CRC cell proliferation by (n-3) PUFA." (PMID 25375205, 2014). "Moreover, the PCNA positive cell count was significantly higher in the insulin-, REO-, or combination-treated groups than in the diabetes group." (PMID 37016650, 2023).
diabetes (continued). "Liver PI3K, liver PCNA and pancreas PCNA were not significantly different in untreated diabetic rats when compared to normal rats suggesting alloxan induction of diabetes did not downregulate the mRNA expression of these genes." (PMID 36301972, 2022). "Studies have shown that diabetes has a negative effect on the expression of PCNA in testicular tissue, and with the progression of diabetes (the increase of blood glucose), PCNA expression shows a significant downward trend, which damages the function of testis." (PMID 34656168, 2021). "DNA replication and DNA repair, as indicated by the expression of proliferating cell nuclear antigen (PCNA), significantly increased during infection (OV) and diabetes (DM) compared to the control hamsters." (PMID 29953446, 2018).
lung adenocarcinoma (22 papers, 2014 to 2025). A carcinoma that arises from the lung and is characterized by the presence of malignant glandular epithelial cells. "Another study considering the resected, early-stage lung adenocarcinoma analyzed PCNA as part of a prognostic phenotype and concluded that higher PCNA expression had statistically significant decreased 5-year overall survival." (PMID 41170373, 2025). "For instance, in most malignancies, including breastinvasive carcinoma (BRCA), lung adenocarcinoma (LUAD), and chronicmyelogenous leukemia (CML), PCNA expression is strongly linked tocell cycle, DNA damage, EMT, and proliferation." (PMID 40657100, 2025). "MiR-363-3p inhibits proliferation and colony formation by targeting PCNA in lung adenocarcinoma A549 and H441 cells." (PMID 37190222, 2023). "To this end, we analyzed the correlation between CKS2 and MKI67 and PCNA, which were involved in the proliferation of lung adenocarcinoma cells, and found that CKS2 was significantly positively correlated with both of the genes." (PMID 36010686, 2022). "By reviewing the literature, it was found that CSE induced the expressions of Ki67, PCNA, and p21 in bronchial epithelial cells and down-regulated the expression of FoxO3a in human lung adenocarcinoma cells." (PMID 36457592, 2022). "Taken together, our data indicate that miR-363-3p suppresses tumor growth by targeting PCNA in lung adenocarcinoma." (PMID 28423618, 2017). "In this study, we found that PCNA is a direct target genes to miR-363-3p in lung adenocarcinoma cancer, and exogenous PCNA expression significantly affect the proliferation of lung adenocarcinoma cells and abrogate miR-363-3p-induced inhibiton." (PMID 28423618, 2017). "Then, we identify PCNA as a direct target of miR-363-3p can rescind miR-363-3p-induced inhibition in lung adenocarcinoma cells." (PMID 28423618, 2017). "In our study, 26 patients underwent PCNA or PCNB and the diagnostic accuracy was found to be 65.4% (17/26) under the IASLC/ATS/ERS classification of lung adenocarcinoma." (PMID 25406492, 2014). "To dissect USP1’s functional interactome, we employed Pearson correlation analysis to assess the relationship between USP1 and proliferation/apoptosis and migration-related markers (Ki-67, PCNA, Bcl-2, N-cadherin) using mRNA expression data from TCGA lung adenocarcinoma samples." (PMID 40136409, 2025). "The study by Wang proved that Mir-363-3p could inhibit the accumulation of endogenous PCNA in lung adenocarcinoma cells, thereby inhibiting lung adenocarcinoma proliferation cells." (PMID 34413873, 2021). "miR-363-3p can decreased the accumulation of endogenous PCNA in lung adenocarcinoma cells." (PMID 28423618, 2017). "Significantly increased expression of PCNA and Ki67 in TPP1 CreCC10 corroborates with a high index of these proteins in human lung adenocarcinoma." (PMID 38344410, 2024). "The GEPIA database prediction results showed positive correlations between the expression of Rad18, PCNA, RPA32 and that of SERTAD2 in lung adenocarcinoma; indeed, the correlation between Rad18 and SERTAD2 was the most significant (R = 0.46, P < 0.0001)." (PMID 35115490, 2022). "Furthermore, we also uncovered the overexpression of some classical oncogenes (FOXA1, PCNA, EZH2) that were reported to mediate carcinogenesis in lung adenocarcinoma along with SUV39H2." (PMID 30348215, 2018). "MKI67, PCNA, and AURKA are largely prognostic in the same cohorts with renal papillary cell carcinoma, lower-grade brain glioma, renal clear cell carcinoma, pancreatic adenocarcinoma, and lung adenocarcinoma." (PMID 32913979, 2017). "Overall, our data reveal an important physiological role for S100-A15 in comprehending the proliferative, metastatic, and invasive properties of lung adenocarcinoma which may be orchestrated by CTNNB1 with the involvement of ZEB1, CDC42, HSP90AA1, PCNA and BST2." (PMID 28498804, 2017).